INS (insulin)
Diseases named in the same sentence as INS in open-access papers (continued):
Sharing a sentence is not in itself a finding about the gene and the disease.
diabetes (continued). "The reduction in daily insulin needs and the optimization of glycemic control improves the patient’s quality of life, self-esteem, mental wellness, as well as diabetes-related mobility and mortality." (PMID 36553284, 2022). "The liver is the classical insulin target organ and plays a key role in control of hepatic glucose homeostasis in diabetes." (PMID 35842638, 2022). "Sixty adolescents with T1D (30 on CSII and 30 on basal-bolus regimen), aged 12–17 years were studied focusing on diabetes-duration, insulin therapy, exercise, socioeconomic standard, hypoglycemic attacks/week and family history of psychiatric illness." (PMID 35379350, 2022). "SIRT1 expression in beta cells helps enhance insulin production to manage glucose levels and prevent the onset of diabetes." (PMID 36225477, 2022). "Leucine also acts at multiple points along the insulin signaling and glucose metabolism pathways playing a role on diabetes development." (PMID 36364703, 2022). "Partial agonists may have more positive effects as PPARγ ligands in diabetes by decreasing adverse effects caused by the activation of unwanted transcription, favored by the binding of full agonists, and by preventing Cdk5-mediated PPARγ phosphorylation, improving insulin sensitivity." (PMID 37746194, 2022). "On the other hand, type 2 diabetes mellitus presents as insulin resistance, where the cells are desensitized from insulin-related signal transduction and mitochondrial exhaustion." (PMID 35890301, 2022). "Diabetes mellitus (DM) is a metabolic condition characterized by persistent hyperglycemia and abnormalities in carbohydrate, lipid, and protein metabolism caused by insulin production, insulin action, or both." (PMID 36225946, 2022). "Diabetes induced an increased blood glucose and serum triglyceride content, a decreased body weight, serum insulin level, and cardiac function-related indexes, accompanied by disrupted myocardial tissue morphology and ultrastructure damage." (PMID 35437457, 2022). "Second, as a mechanistic linker between AD and diabetes, inflammation can accelerate the development of diabetes by influencing islet function and peripheral insulin sensitivity." (PMID 35272707, 2022). "The mice with alloxan-induced diabetes showed a significant elevation of the blood glucose and decreased insulin concentrations by 162% ± 6.8% and 38.8% ± 4.6%, respectively." (PMID 36341058, 2022). "Diet, physical activity and current medications can all help in the control of diabetes (insulin or oral hypoglycaemic drugs such as sulfonylureas and biguanides)." (PMID 35502486, 2022). "Runners stated that they need additional time to include diabetes care (such as analyzing and making insulin and nutritional adjustments) into the general training routine." (PMID 36420398, 2022). "The diagnosis of type 1 diabetes mellitus was placed, and intensified insulin therapy was initiated." (PMID 35918735, 2022). "Compared with enalapril, sacubitril/valsartan lowered HbA1c and reduced new insulin therapy in patients with heart failure with reduced ejection fraction (HFrEF) and diabetes in the PARADIGM-HF trial." (PMID 35717169, 2022). "Type 2 diabetes can be managed with changes in lifestyle, and monitoring of the blood sugar level, along with diabetes medications, insulin or both." (PMID 35808386, 2022). "Histidine can be metabolized to imidazole propionate, which was found to be elevated in individuals with type 2 diabetes mellitus, impairing insulin signaling through activation of the p38γ–p62–mTORC1 pathway." (PMID 35889949, 2022). "Most of the patients with diabetes have insulin defects in insulin secretion, insulin action, or both." (PMID 36326311, 2022). "The data of our work revealed that the untreated diabetic rats exhibited a significant increase in the fasting blood glucose level accompanied by a significant reduction in the insulin serum level indicating the significant clinical signs of diabetes." (PMID 36248064, 2022).
diabetes (continued). "In patients with diabetes, it is suggested to consider metformin or insulin therapy, depending on the presence of symptoms, catabolic signs, glycemia and C-peptide levels." (PMID 35407442, 2022). "In patients with diabetes, the reduction in insulin levels can disturb the biomechanical balance of body tissues, possibly leading to dry eye symptoms." (PMID 35052268, 2022). "Diabetes mellitus is a group of metabolic disorders characterized by hyperglycemia resulting from defects in insulin secretion, insulin action, or both." (PMID 35429987, 2022). "Diabetes mellitus (DM) is a glucose metabolism disorder characterized by chronic hyperglycemia, resulting from a deficit in insulin production and/or action." (PMID 36291558, 2022). "There seems to be a unanimous agreement on the beneficial effects of adiponectin on metabolic conditions such as insulin resistance, diabetes and MetS, due to its insulin-sensitizing effect." (PMID 35872989, 2022). "Continuous glucose monitoring and exogenous insulin administration are considered the mainstay of treatment for diabetes." (PMID 36139388, 2022). "These lesions have clinical effects that reach far beyond the skin—some previous works have shown that lipohypertrophy alters insulin absorption resulting in poor glycemic control and high glycemic variability in persons with diabetes." (PMID 35404833, 2022). "It is already well known that insulin sits at the critical center of metabolic disorders, including obesity, diabetes, hyperlipidemia, non-alcoholic fatty liver disease and all risk factors of cardiovascular disease." (PMID 36345438, 2022). "It is known that in diabetes, the activity of these enzymes is diminished due to insulin inefficiency or resistance." (PMID 36685282, 2022). "Type 2 diabetes mellitus (T2D) is a chronic disease characterized by an elevated concentration of glucose in blood as a result of limited insulin secretion and/or insulin resistance." (PMID 35741012, 2022). "Presently, insulin therapies are the treatment of choice to control hyperglycemia in diabetes mellitus." (PMID 35684464, 2022). "A data driven cluster analysis in European individuals with T2D previously identified four subtypes: severe insulin deficient (SIDD), severe insulin resistant (SIRD), mild obesity-related (MOD), and mild age-related (MARD) diabetes." (PMID 36402758, 2022). "This study found that over the past 3 decades, glycemic control stagnated and racial and ethnic disparities increased among US adults with diabetes using insulin." (PMID 36538330, 2022). "We find that ATP6AP2 is critical for the regulation of insulin and is key to the maintenance of beta cell function and the prevention of diabetes." (PMID 35885938, 2022). "Insulin became available for the treatment of patients with diabetes 100 years ago, and soon thereafter it became evident that the biological response to its actions differed markedly between individuals." (PMID 35323652, 2022). "Nutrition and exercise, including medication use or insulin injection are essential in the management of diabetes for all age groups and gender." (PMID 36564779, 2022). "As an example, imagine a systematic review composed of 60 randomized clinical trials seeking to estimate the effects of a new insulin for treating diabetes." (PMID 36102459, 2022). "Several trials indicated a wide range of approaches, such as modifications in lifestyle and pharmacological treatment, to ameliorate insulin sensitivity and β-cell function, contributing to the prevention of the onset and progression of diabetes." (PMID 36076823, 2022). "Insulin was first used about 100 years ago to save a 14 year old boy who was suffering from type 1 diabetes mellitus." (PMID 35795141, 2022). "Taken together, these observations from animal models suggest that diabetes results from a combination of mechanisms that include decreased beta-cell mass in addition to impaired glucose stimulus insulin secretion coupling." (PMID 35552684, 2022).
diabetes (continued). "Insulin analogs have been developed to treat diabetes with focus primarily on improving the time action profile without affecting ligand-receptor interaction or functional selectivity." (PMID 35177603, 2022). "Evidence indicated that circRNA containing the lariat sequence of the second intron of the insulin gene can regulate insulin secretion in rodent diabetes models and patients with T2D, possibly explaining their impaired secretory capacity." (PMID 36386812, 2022). "Bone marrow adipogenesis in an STZ-induced type 1 model of diabetes in our current study and other previous studies suggests that the process is insulin-independent." (PMID 36307522, 2022). "In this study, all patients with self‐harm intent had a relative with diabetes mellitus which explains the access to insulin or insulin‐secretagogues." (PMID 36117266, 2022). "In this study, the patient was receiving the insulin for diabetes and due to normal blood sugar level, the same insulin regimen was continued during the hospitalization." (PMID 35999988, 2022). "In our study, we obtained similar results with a larger sample size from patients with diabetes receiving stable treatment of insulin." (PMID 36237834, 2022). "Unlike bovine and human milk, previous studies have reported beneficial effects of CM on diabetes and attributed this effect to its high levels of insulin." (PMID 36363614, 2022). "In this study, we have demonstrated that phycocyanin can protect against high glucose high fat diet induced diabetes mellitus in mice and can also ameliorate the insulin-resistant effect of SMMC-7721 cells." (PMID 37430932, 2022). "First envisioned by early diabetes clinicians, a person-centred approach to care was an aspirational goal that aimed to match insulin therapy to each individual’s unique requirements." (PMID 35994083, 2022). "By automatically regulating insulin delivery, an intendedpurpose of this technology is to reduce the burden of diabetes self-management andimprove quality-of-life." (PMID 33472409, 2022). "Galangin induced reduced levels of glucose in skeletal muscles at a higher level than when the cells were treated alone with insulin, what makes it a promising drug for the treatment of diabetes." (PMID 35356248, 2022). "Evaluation of the insulin secretagogue activity, insulin-sensitizing potential, and enzyme inhibition are also common approaches in recent diabetes research." (PMID 36601006, 2022). "The aim of our study was to evaluate the effect of an insulin peptide vaccine formulated with alum to prevent T1D development in female non-obese diabetic (NOD) mice when administered during late-stage pre-diabetes." (PMID 36339431, 2022). "C-peptide is produced with an equal amount of insulin and is the best measure of endogenous insulin secretion in patients with diabetes." (PMID 35574003, 2022). "This diminution causes an increase in the sensitivity to insulin in cells and the secretion of insulin induced by glucose during diabetes, suggesting a possible therapeutic alternative for type 2 diabetes." (PMID 36568514, 2022). "Diabetes mellitus (DM) is a chronic disease characterized by high blood glucose levels owing to decreased insulin secretion or function." (PMID 36205625, 2022). "The primary purpose of this study was to evaluate the effects of oral BBR and inulin combined with insulin therapy on diabetes care in patients with LADA." (PMID 35784546, 2022). "A decrease in insulin release allows high glucose levels to remain in the circulatory system, further exacerbating diabetes." (PMID 36364739, 2022). "Blood glucose is high in diabetes patients because their bodies cannot generate enough insulin or react effectively to this hormone." (PMID 35268815, 2022). "For instance, MafA was first identified as the trans-acting factor binding the RIPE3b/C1 element of the insulin promoter and has since been characterized as an important TF for β-cell function that is dysregulated in diabetes progression." (PMID 35454124, 2022).
diabetes (continued). "Currently, the main drugs used to treat diabetes include insulin, insulin analogues, metformin, sodium-glucose cotransporter-2 (SGLT2) inhibitors, and natural compounds." (PMID 35502441, 2022). "Anti-diabetic medications are currently used to treat diabetes, and their mechanisms include an increase in insulin production, lowering insulin resistance, and blocking glucose reabsorption from the Henley loop." (PMID 35631394, 2022). "We followed the development of diabetes in these mice by assessing fasting blood glucose and insulin every two weeks for 30 weeks to assess the timing of β-cell burnout." (PMID 36145121, 2022). "Diabetes mellitus is characterized by dysregulation of insulin pathway and insulin resistance leading to the disorder of carbohydrate metabolism and hyperglycemia." (PMID 36187088, 2022). "So far, available human data of intermittent fasting focusing specifically on people with type 2 diabetes mellitus treated with insulin, looking into potential glycaemic, body weight and treatment improvements, are mainly limited to case series." (PMID 35179802, 2022). "Regarding type 2 diabetes mellitus and insulin resistance, some studies have revealed a significant influence of gut microbiota on insulin signaling, inflammation, and glucose homeostasis." (PMID 36687699, 2022). "A previous study demonstrated that novel synthesized Mg, Cr, Cu, Ca, Zn, and Se/STG complexes significantly improved insulin secretion and the pancreatic and glycometabolic functions and succeeded in controlling high fat diet-induced diabetes mellitus in rats." (PMID 35678653, 2022). "Obesity measures were the most common outcome of interest and MetS the least (obesity [n = 12]; blood pressure [n = 9]; glucose, insulin or diabetes [n = 6]; lipids [n = 5]; and MetS [n = 3])." (PMID 35954531, 2022). "In short, EMPA restores hypothalamic insulin sensitivity, improves hemoglobin A1c level in the prediabetic patients, and halts the progression of prediabetes to diabetes." (PMID 36168335, 2022). "This leads to a state of glucose intolerance or prediabetes, that eventually produces overt diabetes when pancreatic β cells are incapable of coping with an increased demand for insulin." (PMID 36057662, 2022). "Diabetes Mellitus, also named autoimmune diabetes or Type 1 diabetes mellitus, is a chronic immune-mediated illness depicted by insulin defects due to pancreatic islet beta-cell damage with growing blood glucose levels." (PMID 35632243, 2022). "Diabetes is defined as an uncontrollable level of glucose in the bloodstream due to inadequate insulin production by the pancreas." (PMID 35744089, 2022). "Children who had and had not been affected by COVID-19 were not different in terms of gender, parents' education, household dynamics, diabetes duration, insulin regimen, or family history of T1D." (PMID 36620301, 2022). "Xanthurenic acid is a metabolite of tryptophan which has been found to be conductive to development of diabetes through chelating complexes with insulin and hence inducing pathological apoptosis of pancreatic β cells." (PMID 36204098, 2022). "These mild phenotypes are distinct to that of mice lacking OGT in their β-cells, where they develop severe hyperglycemia and over diabetes in early adulthood in part by decreased β-cell mass and insulin secretion failure." (PMID 36387851, 2022). "Most patients took at least one diabetes medication (85.71%) and 81 (32.14%) patients needed insulin therapy." (PMID 34255166, 2022). "Growth hormone (GH) is important for regulating insulin secretion and carbohydrate metabolism, and its role in mammalian models of diabetes is relatively worked out." (PMID 36561570, 2022). "Compared to normal weight patients, obese patients were significantly younger—OR 0.98 (0.96–0.99), and with insulin-dependent and non-insulin-dependent diabetes mellitus—OR 1.83 (1.09–3.06) and OR 2.13 (1.50–3.01) respectively." (PMID 36538553, 2022).
diabetes (continued). "These have great clinical implications as physicians should be aware of the time and risk factors of hypoglycemia and their exaggerated fears and perceptions mean delaying insulin initiation and, subsequently, more diabetes-related complications." (PMID 36554673, 2022). "Diabetes mellitus (DM) is a chronic disease, characterized by hyperglycemia and dysfunction of insulin secretion and sensitivity, which has shown a steep increase in incidence and prevalence each year." (PMID 36501700, 2022). "It declines, however, in prediabetes and even more in some subjects with diabetes, which have in part considerably reduced beta-cell function and/or insulin sensitivity." (PMID 36271244, 2022). "A multiple linear regression model adjusted for age, sex, diabetes duration and use of continuous subcutaneous insulin infusion was constructed to estimate the difference in change from baseline HbA1c between the two groups and within subgroups of T1D-CGM." (PMID 36240184, 2022). "More relevantly, NSD2 has been demonstrated to be downregulated in patients with diabetes mellitus, and its upregulation increased insulin secretion and reduced glucose concentration through promoting pancreatic β cell proliferation." (PMID 35354439, 2022). "Type 2 diabetes mellitus is characterized by the disturbance of glucose homeostasis, involving impaired insulin response to regulate glucose utilization in peripheral tissues, including skeletal muscle, adipose, and liver." (PMID 34073781, 2021). "According to the World Journal of Diabetes, diabetes mellitus is a chronic metabolic disorder in which the body's ability to produce or reciprocate to insulin is lost, resulting in impaired carbohydrate metabolism and increased levels of glucose in the blood." (PMID 34295586, 2021). "Based on insulin availability, diabetes can be classified into Type I insulin-dependent, Type II insulin-independent, Idiopathic diabetes and Gestational diabetes, and Type I and Type II diabetes are the most common ones." (PMID 33467677, 2021). "This is the first report of guinea pigs with insulin-dependent diabetes mellitus that were successfully treated with long-acting basal insulin glargine." (PMID 33916377, 2021). "The development of diabetes begins in the prediabetic stage, wherein the fasting plasma glucose levels are elevated due to peripheral resistance to insulin." (PMID 34276388, 2021). "The survey did not collect any data about diabetes type, duration of illness, treatment (insulin, tablets and combinations) or diabetes-specific complications." (PMID 35146310, 2021). "STZ damage to the pancreatic islet of Langerhans β-cells leads to a low level of insulin production in diabetic rats, and it leads to the increase in the plasma glucose levels turning to diabetes." (PMID 34924860, 2021). "Major advancements within diabetes research have been made since the ground-breaking discovery of insulin in the early 1920s." (PMID 35126141, 2021). "Surprisingly, we found substantial use of these CCDs, especially simple sugar CCDs, even in patients with diabetes who take insulin." (PMID 34044894, 2021). "To study the response of insulin-treated zebrafish larvae to anti-diabetes drugs, we evaluated the free glucose level with pioglitazone (PIO) treatment." (PMID 34358068, 2021). "Adiponectin is in essence acting as an insulin sensitizer, and has been found to reduce the effects of hyperglycemia and insulin resistance when administered to people with diabetes." (PMID 33806509, 2021). "Patients with diabetes type 2 usually are insulin resistant and the blood level of insulin also depends on the stage of diabetes." (PMID 33921222, 2021). "Initial studies have shown that this receptor has an important effect on fat cells and insulin, and is one of the research targets for the treatment of diabetes." (PMID 34234785, 2021).